RPL17P50 (ribosomal protein L17 pseudogene 50)
Gene: Processed pseudogene on chromosome 10 (73,005,833 to 73,006,595, reverse strand). Ensembl gene ENSG00000213700.
Diseases named in the same sentence as RPL17P50 in open-access papers:
RPL17P50 is named in the same sentence as 1 disease in open-access papers, as found by Europe PMC text mining. Sharing a sentence is not in itself a finding about the gene and the disease. The quoted sentences say what the papers report.
cancer (1 paper, 2022). A tumor composed of atypical neoplastic, often pleomorphic cells that invade other tissues. "The corresponding heatmap analysis also indicated a positive correlation between P4HA1 and these five genes (BNIP3L, FUT11, LDHA, PGK1, and RPL17P50) in the majority of 32 types of cancers." (PMID 35812752, 2022).